NOD1 (nucleotide binding oligomerization domain containing 1)
Diseases named in the same sentence as NOD1 in open-access papers (continued):
Sharing a sentence is not in itself a finding about the gene and the disease.
glioma (continued). "Although the NOD1/RIP2 pathway has been implicated in various inflammatory responses, its role in glioma remains unclear." (PMID 41363048, 2025). "This study aimed to investigate the role of the NOD1/RIP2 pathway in glioma progression." (PMID 41363048, 2025). "NOD1 is an effective predictor of preoperative glioma grade and prognosis." (PMID 41363048, 2025). "The effects of ML130 and ie‐DAP on glioma growth rates in rats were analyzed to assess whether the NOD1/RIP2 pathway could influence glioma progression." (PMID 41363048, 2025). "The high NOD1 expression may therefore indicate malignant features in glioma, although the precise mechanism of NOD1 in glioma progression remains unclear." (PMID 41363048, 2025). "Thus, NOD1 can serve as a biomarker for glioma diagnosis and a target for treatment." (PMID 41363048, 2025). "Finally, the role and mechanism of NOD1 in glioma growth were evaluated using a rat glioma model." (PMID 41363048, 2025). "Furthermore, the expression levels of genes encoding NLR proteins (NLRP12, NOD2, NOD1, NLRC4, and NAIP), inflammasome adaptor molecules (PYCARD), and proinflammatory caspases (CASP1, CASP4, and CASP5) were significantly higher in glioma patients than in normal controls." (PMID 31133717, 2019). "This study aimed to highlight the role of the NOD1/RIP2 pathway in glioma progression, providing a theoretical basis for novel glioma treatments." (PMID 41363048, 2025). "NOD1 influences microglial M2 polarization by regulating the NOD1/RIP2 pathway, thereby promoting glioma progression." (PMID 41363048, 2025). "C6 and U251 glioma cells were treated with ML130, a NOD1 inhibitor, and assessed using 5‐ethynyl‐2′‐deoxyuridine (EdU), plate cloning, Transwell, and wound healing assays." (PMID 41363048, 2025). "Human brain glioma samples exhibited increased expression of NOD1, RIP2, Iba1, interleukin‐1β, and CD206, with higher expression in high‐grade gliomas compared to low‐grade gliomas." (PMID 41363048, 2025). "T2‐weighted imaging (T2WI) MRI combined with various histologic techniques were used in in vivo experiments to investigate how the NOD1/RIP2 pathway affects microglial M2 polarization and glioma progression." (PMID 41363048, 2025). "The IHC results showed that in the Glioma + ML130 group, the OD values of NOD1, RIP2, Iba1, IL‐1β, and CD206 were lower than those in the Glioma group (p < 0.05)." (PMID 41363048, 2025). "The relationship between the NOD1/RIP2 pathway and microglial polarization was investigated by performing IHC and WB analyses on human non‐tumor brain and glioma tissues." (PMID 41363048, 2025). "WB results exhibited relative protein expression levels of NOD1, RIP2, Iba1, IL‐1β, and CD206 in glioma tissues in the Glioma group that were higher than in the Sham group (p < 0.05), with decreased expression following ML130 treatment." (PMID 41363048, 2025). "The results indicated that NOD1, RIP2, Iba1, IL‐1β, and CD206 were highly expressed in glioma tissues, with higher expression in high‐grade gliomas than in low‐grade gliomas." (PMID 41363048, 2025). "The results indicate that NOD1 can promote microglial cell polarization through RIP2, thereby influencing the biological behavior of glioma cells." (PMID 41363048, 2025). "This suggests that the NOD1/RIP2 pathway may regulate microglial M2 polarization, thereby influencing glioma growth." (PMID 41363048, 2025). "Although macrophages can modulate tumor growth and invasion by NOD1 activation, the effect of the NOD1/RIP2 pathway on microglial polarization and glioma progression remains unclear." (PMID 41363048, 2025). "However, the roles of CASP1, NOD1, NLRC4 and NLRP12 are not reported in relation to glioma." (PMID 31186453, 2019).
atopic dermatitis (8 papers, 2012 to 2025). "In atopic dermatitis cohorts NOD1 SNPs were associated with increased IgE levels, and more weakly with atopic dermatitis, while a polymorphic NOD2 allele was associated with an almost 2-fold risk of atopic dermatitis." (PMID 33925158, 2021). "Furthermore, a missense variant of NOD2 and a rare NOD1 haplotype were observed more frequently in patients with atopic dermatitis than in control subjects." (PMID 33925158, 2021). "While its role in canine atopic dermatitis remains unclear, human studies suggest that S. flexneri activates epithelial cell NLRs, thereby triggering inflammatory responses, particularly via NOD1 recognition." (PMID 41227429, 2025). "Though NOD1/2 signaling is typically associated with pathogen recognition and innate immune responses, genetic variants in NOD1 and NOD2 have been associated with atopic dermatitis 58–60, suggesting a role in allergic inflammation." (PMID 40470207, 2025). "Genetic variants for both NOD1 and NOD2 (and also NLRP12) are linked to atopic dermatitis." (PMID 33925158, 2021). "This interaction may enhance NOD1 signaling through NLR family pyrin domain containing 10 (NLRP10) expression in epidermal and dermal fibroblast-like cells, potentially influencing innate immune responses and exhibiting the associations with atopic dermatitis and allergic contact dermatitis." (PMID 41227429, 2025).
metabolic syndrome (8 papers, 2017 to 2025). A cluster of metabolic risk factors for CARDIOVASCULAR DISEASES and TYPE 2 DIABETES MELLITUS. "In humans, studies have demonstrated markedly increased expression of NOD1 in individuals with metabolic syndrome." (PMID 40871707, 2025). "NOD1 expression was upregulated in the adipose tissue of patients with metabolic syndrome or gestational diabetes." (PMID 36920176, 2023). "Like the DKO, the NOD1-/- mice were resistant to the development of HFD-induced metabolic syndrome, and this effect was mediated by both hematopoietic and non-hematopoietic cells." (PMID 37869013, 2023). "In contrast, to the role of NOD1 in promoting metabolic syndrome, NOD2 was demonstrated to counteract it." (PMID 37869013, 2023). "Similar to Nod1/2−/− mice, Nod1−/− mice were protected against development of metabolic syndrome when fed a HFD." (PMID 33503814, 2021). "In contrast, there are human studies demonstrating highly upregulated expression of NOD1 and NOD2 in individuals with metabolic syndromes." (PMID 33503814, 2021). "Although both NOD1 and NOD2 are expressed in adipose tissue, only NOD1 expression is elevated in obese patients, individuals with metabolic syndrome, or mice fed a HFD." (PMID 33503814, 2021). "Activation of NOD1 and NOD2 is involved in the development of metabolic syndromes." (PMID 36268029, 2022).
hepatocellular carcinoma (7 papers, 2011 to 2024). A malignant tumor that arises from hepatocytes. "For example, NOD1/2 activation and deficiency as well as the intake of a diet rich in lipids and certain signals of cellular damage are closely related to cell proliferation and the response(s) to chemotherapy in hepatocellular carcinoma (HCC)." (PMID 38397943, 2024). "Conversely, NOD1 can induce cell apoptosis and inhibit cell proliferation in papillary thyroid carcinoma and hepatocellular carcinoma." (PMID 38437016, 2024). "Compared with normal liver tissues, the expression level of NOD1 in hepatocellular carcinoma tissues was significantly downregulated, and the increased expression level of NOD1 significantly inhibited the proliferation of tumor cells." (PMID 36186792, 2022). "Here we hypothesize that Evo exerts anti-hepatocellular carcinoma activity by inhibiting NOD1 to suppress NF-κB and MAPK activation." (PMID 30384473, 2018). "In hepatocellular carcinoma (HCC), NOD1 exerts an anti-tumor function by targeting the proto-oncogene SRC, leading to cell cycle arrest in the G1 phase and inhibition of the SRC–MAPK axis." (PMID 39329913, 2024). "Therefore, we hypothesize that Evo exerts anti-hepatocellular carcinoma activity by inhibiting NOD1 to suppress NF-κB and MAPK activation." (PMID 30384473, 2018). "Therefore, we proved the anti-hepatocellular carcinoma activity of Evo on HCC cells and detected the effect of Evo on the NOD1 pathway." (PMID 30384473, 2018).
lung carcinoma (7 papers, 2019 to 2024). "Taken together, these findings reveal that HOXC10 effectively alleviates pan-KRAS-mutant lung cancer with bone metastasis in the NOD1/ERK axis-dependent manner, and support further development of an effective combinatorial strategy for this kind of disease." (PMID 39191757, 2024). "It was also found that polymorphisms of NOD1/CARD4 may affect the diagnosis and treatment of lung cancer, while polymorphisms of NOD2 were also associated with an increased risk of lung cancer." (PMID 34805165, 2021). "Taken together, our work indicates that HOXC10/NOD1/ERK signaling can be a promising target for preventing and treating lung cancer bone metastasis." (PMID 39191757, 2024). "However, the role of NOD1 in lung cancer has not been studied." (PMID 36186792, 2022).
ovarian carcinoma (6 papers, 2019 to 2024). A malignant neoplasm originating from the surface ovarian epithelium. "NOD1/2 act as an oncogene in ovarian cancer by upregulating immune-related pathways such as the RIPK2/NFκB signaling pathway." (PMID 39149564, 2024). "NOD1 can promote tumor progression by activating NF-κB signaling in ovarian cancer and esophageal squamous cell carcinoma." (PMID 38437016, 2024). "Through miRNA, these lncRNAs are connected with PRGs such as IRF1, NOD1, GSDMC, NLRP1, PLCG1, GSDME and GZMB to construct a pyroptosis related ceRNA regulatory network in ovarian cancer." (PMID 37859811, 2023). "Equally, NOD-1 protein was found to phosphorylate NF-κB by binding to the protein receptor that interacts with serine/threonine kinase 2 (RIPK2), enhancing the proliferative and invasive properties of ovarian cancer cell lines." (PMID 37624039, 2023). "In addition, several other potentially interesting targets of YTHDF2 in ovarian cancer have been identified, such as the putative tumor suppressors TRERF1, ZDHHC14, DIS3L, Vps18, NOD1, and SLC9A8." (PMID 33658012, 2021).
sarcoidosis (6 papers, 2012 to 2021). Sarcoidosis is a multisystemic disorder of unknown cause characterized by the formation of immune granulomas in involved organs. "An investigation of NOD1 gene polymorphisms in Japanese sarcoidosis patients suggested the involvement of the NOD1 796A-allele, which is linked to reduced NOD1 expression and decreased NF-κB activation due to intracellular P. acnes." (PMID 27219015, 2016). "A systematic search for NOD1 gene polymorphisms in Japanese sarcoidosis patients identified two alleles, 796G-haplotype (156C, 483C, 796G, and 1722G) and 796A-haplotype (156G, 483T, 796A, and 1722A)." (PMID 23844371, 2013). "It is possible that impaired expression of beta-defensin 2 through 796-A NOD1 due to a reduced ability to induce NF-κB enables P. acnes to survive and persist intracellularly, leading to the pathogenesis of sarcoidosis." (PMID 23844371, 2013). "Sarcoidosis patients may be prone to latent M. tuberculosis and P. acnes infection due to unknown host factors including decreased expression levels of nucleotide-binding oligomerization domain-containing protein 1 (NOD1) in response to intracellular infection by these gram-positive bacteria." (PMID 33801218, 2021). "We also compared the expression levels of NOD1 mRNA (also known as CARD4), in pulmonary leucocytes obtained from BD and sarcoidosis patients and healthy controls." (PMID 22330585, 2012).
cervical cancer (5 papers, 2020 to 2025). A primary or metastatic malignant neoplasm involving the cervix. "Combined with the down-regulation of NOD1 expression in CINs and ISCCs, we suggest that the dysregulation of NOD1-mediated inflammation may be an important risk factor in cervical intraepithelial neoplasia and cervical cancer." (PMID 32021648, 2020). "As the cervix is often in contact with pathogenic microorganisms, we speculate that NOD1-related signal pathway may be involved in the occurrence of cervical cancer." (PMID 32021648, 2020). "constructed a new prognosis predication model based on 8 risk-related PRGs (GPX4, GSDME, GZMA, GZMB, IL1B, NOD1, PRKACA, and TNF) in cervical cancer, which had good predictive ability (AUC = 0.794)." (PMID 35912258, 2022). "In order to understand the possible function of NOD1 in cervical cancer, we first profiled its expression in CINs and ISCCs tissues by immunostaining." (PMID 32021648, 2020). "The expression of NOD1 was examined by immunocytochemistry in 3 cervical cancer cells: SiHa infected with type 16 HPV, the predominant HPV type (46–63%) in cervical squamous cell carcinoma; ME180 infected with type 68 HPV; and C33A without HPV infection." (PMID 32021648, 2020). "When NOD1 protein was examined using Western blot in 3 paired tumor (T) and adjacent normal (N) tissues from cervical cancer patients, NOD1 level in normal tissues was higher than that in cancer tissues." (PMID 32021648, 2020). "We found that NOD1 in cervical cancer cells can be activated by iE-DAP, consequently facilitating the CHX-induced apoptosis." (PMID 32021648, 2020). "In the current study, we investigated the expression of NOD1 in different grade cervical lesions, the impact of HPV infection on NOD1 expression, and the role of NOD1-mediated signaling in cervical cancer." (PMID 32021648, 2020). "In the study, we revealed that NOD1 expression decreased during the progression of cervical intraepithelial neoplasia to cervical cancer and that HPV16 E6/E7 oncoproteins induced down-regulation of NOD1." (PMID 32021648, 2020). "A recent study showed that downregulation of NOD1 promoted CIN progression to cervical cancer." (PMID 35130902, 2022). "We investigated the effect of NOD1 on apoptosis of hrHPV-infected cervical cancer cells." (PMID 32021648, 2020). "The data indicated that the dysregulation of NOD1-mediated inflammation and apoptosis may contribute to cervical intraepithelial neoplasia progression and cervical cancer." (PMID 32021648, 2020). "The results indicated that NOD1 can enhance the sensitivity of HPV16-positive cells to apoptosis induced by CHX and the decrease of NOD1 expression may contribute to the apoptosis resistance and the development of cervical cancer." (PMID 32021648, 2020). "Moreover, the activation of NOD1 promoted the apoptosis of HPV16-positive cervical cancer cells." (PMID 32021648, 2020). "Compared with normal cervical tissues, the expression of NOD1 mRNA in cervical cancers decreased, although the difference was not statistically significant." (PMID 32021648, 2020). "Our results suggested that the down-regulation of NOD1 by HPV16 E6/E7 can reduce cell apoptosis, which may promote the development and progression of cervical cancer." (PMID 32021648, 2020).
chlamydial infection (5 papers, 2014 to 2025). "While NOD1 has been implicated in CXCL8 expression after chlamydial infection in vitro, it was shown that the siRNA knockdown of NOD1 expression in HeLa cells only resulted in a partial inhibition of CXCL8 secretion." (PMID 27002636, 2016). "Thereby, YkfC breaks down the minimal peptidoglycan recognition motif of NOD1 and abolishes sensing of chlamydial infection—as suggested from our combined biochemical enzyme activity and in vivo NOD1 activation analyses." (PMID 36730465, 2023). "Both intracellular TLR2 and the NOD1 intracellular pattern recognition receptor, which detects specific motifs in bacterial peptidoglycan, have been implicated in the induction of a CXCL8 response to chlamydial infection." (PMID 27002636, 2016). "Because Apaf-1 shares domains with intracellular innate immune receptor NOD1, it may play a key role in the strategy to regulate chlamydial infection." (PMID 26290316, 2015). "In addition to TLR2, the NOD1 intracellular pattern recognition receptor, which detects specific motifs in bacterial peptidoglycan, has also been implicated in the induction of a CXCL8 response to chlamydial infection." (PMID 25010668, 2014). "Nod1 and Nod2, which also contain the CARDs, were implicated as intracellular sensors that recognize patterns of intracellular pathogens, while expression of both Nod1 and Nod2 in HEp-2 cells were not modified by chlamydial infection based on a DNA microarray analysis (data not shown)." (PMID 26290316, 2015).
COVID-19 (5 papers, 2021 to 2023). A disease caused by infection with severe acute respiratory syndrome coronavirus 2. "Severe COVID-19, however, is characterized by additional activation of TLR1, TLR2, TLR4, TLR5, TLR6, NOD1 and NOD2, which are primarily responsive to bacterial antigens." (PMID 36769320, 2023). "Upregulated genes in early COVID-19 mortality included many involved with interferon signaling (e.g., GBP2, ISG15), the NF-κB pathway (e.g., NFKB2, NFKBIA), and TNF-α and IL-1 signaling (e.g., TANK, NOD1, RELA)." (PMID 35446789, 2022). "One final complication is that many severe COVID-19 patients are treated with multiple antibiotics, which may further modify the expression of bacterially activated TLR and NOD1/NOD2." (PMID 33672738, 2021). "Consistent data indicate that TLR1, TLR5, TLR6, TLR8, NOD1, NOD2 and RIG1 are not activated in severe COVID-19." (PMID 33672738, 2021).
gastritis (5 papers, 2010 to 2021). Inflammation of the stomach. "NOD1 polymorphisms were also often linked to inflammatory reaction following Helicobacter pylori infection, such as duodenal ulcer and gastritis." (PMID 27069792, 2016). "The majority of patients with H. pylori-associated gastritis have a higher NOD1 expression in gastric epithelial cells as compared with controls or H. pylori-nonassociated gastritis, which suggests the involvement of NOD1 signaling in the development of human gastric inflammation." (PMID 21152124, 2010). "Although IL-33 reportedly plays a pivotal role in gastritis exacerbation, a recent study revealed that NOD1 is required for H. pylori-induced IL-33 production and that this confers a protective role against inflammation." (PMID 31640262, 2019).
acute pancreatitis (4 papers, 2015 to 2024). An acute inflammatory process that leads to necrosis of the pancreatic parenchyma. "Synergistic interactions between signaling pathways mediated by CCKR and NOD1 underlie the pathogenesis of acute pancreatitis associated with bacterial translocation." (PMID 38440723, 2024). "NOD1-deficient mice are resistant to experimental acute pancreatitis and CP induced by cerulein, indicating that NOD1 is involved in the pathogenesis of pancreatitis induced by CCKR activation." (PMID 34759844, 2021). "We found that mice deficient in NOD1 and TLR4 were resistant to cerulein-induced acute pancreatitis and that bowel sterilization by a broad range of antibiotics prevented the development of acute pancreatitis." (PMID 38440723, 2024). "Conversely, it has also been shown that the initial onset of cerulean-driven acute pancreatitis is dependent on the activation of NOD1 in acinar cells by commensal bacteria translocated from the gut, which further induces the expression of inflammatory mediators." (PMID 26347203, 2015). "Similarly, TLR4 and NOD1 knockdown mice are protected from acute pancreatitis." (PMID 26347203, 2015).
Blau syndrome (4 papers, 2009 to 2024). Blau syndrome (BS) is a rare systemic inflammatory disease characterized by early onset granulomatous arthritis, uveitis and skin rash. "Compelling evidence indicates that NOD1 and NOD2 polymorphisms are involved in a great number of immunologic and inflammatory diseases, including Crohn’s disease (CD), Blau syndrome, Behcet’s syndrome, ulcerative colitis (UC), atopic diseases, and early-onset sarcoidosis (EOS)." (PMID 34557182, 2021). "Defective S-palmitoylation of NOD1/2 leads to severe immunologic and inflammatory diseases, including Crohn’s disease (CD), ulcerative colitis (UC), Blau syndrome, Behcet’s syndrome, early-onset sarcoidosis (EOS), and atopic diseases." (PMID 38970666, 2024).